IL1B (interleukin 1 beta)
Diseases named in the same sentence as IL1B in open-access papers (continued):
Sharing a sentence is not in itself a finding about the gene and the disease.
influenza (continued). "Our results showed that indirubin treatment lessened the production of TNF-α, IL-1β and IL-6 while enhanced the production of IL-10 in the lung tissues of influenza-infected mice loaded with stress." (PMID 29285277, 2017). "As L. paracasei feeding, before or after influenza infection, induced secretion of IL-1β and IL-33, we focused our attention on the presence of cytokine-expressing ILCs and T cells." (PMID 28931041, 2017). "Upon entry into respiratory epithelial cells (upper and lower respiratory tract and alveolar cells), influenza triggers production of several pro-inflammatory cytokines and chemokines such as interferons, IL-1β, IL-8, IL-6 and TNF-α19." (PMID 28106111, 2017). "TNF-α and IL-1β are important proinflammatory cytokines and contribute directly to the severity of gross and histologic lung lesions in the influenza infected mice." (PMID 27110056, 2016). "In this study, we report that interleukin-1β (IL-1β) and interleukin-17A (IL-17A) are key mediators of neutrophilic inflammation in influenza-induced exacerbations of chronic lung inflammation." (PMID 24918427, 2014). "Taken together our data demonstrated that blocking of IL-17A or IL-1β signaling during influenza-induced exacerbations diminished neutrophilic infiltration at distinct phases of infection." (PMID 24918427, 2014). "In order to investigate the role of IL-1β during COPD exacerbations we utilized a model of LPS and elastase induced chronic lung inflammation, followed by infection with influenza in wild type or IL-1β deficient mice." (PMID 24918427, 2014). "Surprisingly, the triple combination of IFNβ, TNFα, and IL1β reduced influenza-induced cell death in infected DCs." (PMID 24616721, 2014). "We further report a role for IL-17A as a mediator of IL-1β induced neutrophilia at early time points during influenza-induced exacerbations." (PMID 24918427, 2014). "Building upon these studies we found that during influenza-induced exacerbations, pulmonary accumulation of neutrophils was also driven by IL-1β." (PMID 24918427, 2014). "In influenza infection, IL-1β bind with its receptors leads to the activation of multiple cytokines, including TNF-α which plays an important role in the early stages of host defense against influenza infection." (PMID 25547136, 2014). "Expression of the main neutrophil chemoattractants CXCL1, CXCL2, and CXCL5 were induced upon influenza infection, but were unaffected by IL-1β." (PMID 24918427, 2014). "In conclusion our data demonstrated that IL-1β influenced neutrophilic inflammation during influenza-induced exacerbation of chronic lung inflammation in mice throughout the entire phase of viral replication." (PMID 24918427, 2014). "Thus, it is possible that IL1B SNP rs1143627 C allele has a lower binding affinity to c/EBPβ and reduced levels of IL-1B expression, which may therefore weaken the inflammatory response of Th-17 and Th-1 cells in humans during influenza infection." (PMID 23927441, 2013). "To further validate the cross-talk between RIG-I, type I IFN, and IL-1β during IAV infection, we investigated the impact of influenza NS1 variants with a known effect on virulence and on the type I IFN response in ferrets." (PMID 23592984, 2013). "A protective interleukin 1β (IL-1β) response primarily mediated by macrophages and lung epithelial cells is a key component of the innate immune response to influenza infection." (PMID 23592984, 2013). "Other downregulated genes after 2-days were pik3r5, akt3a, nfkbiab, hras, mapk14a in hepatitis, pik3r5, akt3a, il1b, il12a, raf1b, map2k1 in influenza and pik3r5, akt3a, nfkbiab, il1b, il12a in measles." (PMID 24069208, 2013). "Over-expression of several regulated cytokines including IL-1α, IL-1β, TNF-α, and IFN-γ have been associated with morbidities in influenza infection, and spontaneous pregnancy loss." (PMID 22792357, 2012).
influenza (continued). "ADAMTS7 has also been shown to be upregulated by TNF-α and IL-1β secretion, both of which are activated upon influenza infection." (PMID 22606348, 2012). "Three additional reports examined the role of IL-1β, as well as components of the Nlrp3 inflammasome, in control of influenza infection." (PMID 23056330, 2012). "In particular, studies on influenza virus demonstrated that IL-1β is responsible for the acute lung pathology, and the inflammasome pathway that produce IL-1β has been shown to be essential in the inflammatory response against influenza infection." (PMID 22558229, 2012). "A recent report showed in mouse model that Nlrp3 inflammasome activation depends on reactive oxygen species (ROS) and inhibition of ROS induction abolished IL1B production during influenza infection." (PMID 21901105, 2011). "For example, the roles of the NLRP3 inflammasome and IL-1β in influenza infection remain debated." (PMID 40983621, 2025). "Interestingly, the trend of downregulation of IL-1β in our mouse model is consistent with the findings in human patients with IAPA versus influenza alone." (PMID 39949778, 2025). "aQIV-vaccinated mice also had no increase in influenza-associated inflammatory cytokines like IL-1β, TNFα, IL-2, and IL-6." (PMID 39975920, 2025). "Artemisinin-derived artesunate (ART) significantly reduces the expression of TNF-α, IL-6, and IL-1β in the lung tissue of influenza-infected mice by inhibiting the TLR4/NF-κB (p65) axis, with a lung index reduction of over 30%, and significantly improves body weight and survival rate." (PMID 40860873, 2025). "Furthermore, using a B cell specific IL-1β KO mouse model we also show that B cell derived IL-1β is essential for optimal GC formation in influenza infection." (PMID 40825032, 2025). "Therefore, it is important for us to rule out other inflammasome activities as being significant for IL-1β driven GC function post influenza infection." (PMID 40825032, 2025). "Collectively, our findings are significant as we have identified the vital source of IL-1β within the GC post influenza infection and identified the inflammasome that drives the production of this cytokine, which has conventionally been associated with innate cells." (PMID 40825032, 2025). "IL‐1β production by (senescent) macrophages might play a role in driving pulmonary fibrotic sequelae post‐influenza." (PMID 40541563, 2025). "Malic acid showed strong negative associations with TNFα, IL-6, and IL-1β cytokine levels upon influenza stimulation." (PMID 39331702, 2024). "Influenza infection also induces IL-1β, resulting in lung inflammation." (PMID 39000173, 2024). "Similarly, in vitro experiments show that when infected with the H5N1 strain of influenza, limited viral replication was seen in astrocytes despite significant production of IL-1β." (PMID 37649972, 2023). "Moreover, a recent study in humans administered with live attenuated influenza vaccine and S. pneumonia reported that expression of IL-1β was reduced, whereas expression of the IRF3/IFN-β-driven cytokine IP-10 was increased." (PMID 37435074, 2023). "In addition, Mfn2 binds to NLRP3 to promote IL-1β secretion after infection with RNA viruses, including influenza, measles, or EMCV." (PMID 35958608, 2022). "The exosomes of the infected A549 cells were found to enhance M1 polarization (iNOS/Arg-1, Tnfα/Arg-1, and IL-1β/Arg-1) in a better way, thereby indicating that exosomes might play an essential role in influenza-mediated macrophage polarization." (PMID 35371077, 2022). "Moreover, Z-DNA-binding protein 1 (ZBP1), a novel effector of necroptosis, triggers NLRP3 inflammasome activation and release of IL-1β through the RIPK1-RIPK3-Caspase-8 axis during influenza A virus (IAV) infection." (PMID 36619743, 2022). "The elderly tended to produce more IL-1β and IL-1RA, while young individuals could produce higher IFNγ amounts upon influenza stimulation." (PMID 34434199, 2021).
influenza (continued). "Combined stimulation with influenza and R848 resulted in markedly increased production of pro-IL-1β (153.9%, p = 2.22 × 10−16) and IL-1β (339.8%, p = 2.22 × 10−16), with more moderate but significant increases in caspase-1 (32.0%, p = 0.009) and IL-18 (8.5%, p = 2 × 10−5)." (PMID 35822051, 2021). "rAd-IL-1β-adjuvanted immunization increased mucosal and systemic T cell immune responses, local tissue-resident memory T cell population, and improved protection against heterologous influenza strains H1N1, pH1N1, H3N2, and H7N7." (PMID 33430259, 2021). "Similarly, elderly mice infected with influenza exhibited lower levels of 1L-1β, and administration of IL-1β augmenting compound improved morbidity and mortality." (PMID 33571320, 2021). "We also conducted multiplex measurement on cytokines and chemokines at day 7 p.i. in lung tissues using Luminex 200, and similarly, we found significantly higher production of IL-1β, IL-6, TNF-α, IL-10, MCP-1, IP-10, and IFN-γ caused by influenza infection on day 7 p.i.." (PMID 35154087, 2021). "A previous study showed that IL-1β as a mucosal vaccine adjuvant led to the expression of chemokines and adhesion molecules, as well as induced local Trms, which improved the heterosubtypic immunity against influenza." (PMID 34571913, 2021). "Notably in this regard, the impairment in inflammasome activity is rescued to some extent by Nig treatment, which increases caspase‐1‐augmented IL‐1β production during influenza infection." (PMID 32428336, 2020). "Similarly using a murine model it was revealed that IL-1β production is inhibited by IFN-γ during influenza infection." (PMID 33634060, 2020). "The dynamic interplay between IFN-β and IL-1β could provide a novel mechanism for the pathogenesis of influenza and bacterial co-infections." (PMID 32008371, 2020). "TNF-α stimulates IL-1β which exacerbates lung injury during severe influenza but may also have a vital role in lung repair after infection." (PMID 32599823, 2020). "For instance, interleukin-1β (IL-1β) and interleukin-17A (IL-17A) may mediate neutrophilic inflammation in influenza-initiated exacerbation of chronic lung inflammation." (PMID 31307416, 2019). "Furthermore, sorted alveolar macrophages from influenza-infected mice exhibited increased expression of pro-IL-1β and inflammasome components, which was unaltered by neutrophil depletion." (PMID 29079611, 2018). "An abundance of literature has demonstrated that the NLRP3 inflammasome is central to influenza-induced IL-1β production, with alveolar macrophages deemed to be the prominent source of the cytokine, 20 23–25 and we provide several lines of evidence to support this assertion." (PMID 29079611, 2018). "Finally, immunohistochemical IL-1β staining was solely restricted to macrophages of influenza-infected mice in our model." (PMID 29079611, 2018). "To infer whether this absolute requirement of neutrophil recruitment for IL-1β release was influenza specific, we assessed the consequence of neutrophil depletion in other respiratory infectious models." (PMID 29079611, 2018). "While our data strongly support the notion that mCRAMP can drive alveolar macrophage IL-1β release during influenza infection, it is feasible that other neutrophil-derived signals may also contribute." (PMID 29079611, 2018). "It remains possible that the inflammasome-stimulating activity of flagellin could augment protection against viral or bacterial infections for which IL1-β is a key component, such as influenza and Pseudomonas aeruginosa." (PMID 29562688, 2018). "Therefore, further studies on the effects of inflammatory cytokines, including IL-1β on these hemagglutinin processing proteases are needed to understand the pathogenesis of multiple organ failure in severe influenza." (PMID 27714503, 2017).
influenza (continued). "Infection with highly pathogenic influenza such as H5N1 and H7N9 induces extensive infiltration of macrophages and neutrophils, upregulation of pro-inflammatory cytokines such as TNF-α, IL-1β, IL-6, IL-8 and IP-10, and cell death resulting in severe pulmonary inflammation." (PMID 27315117, 2016). "Syncytin-1 exposure leads to a marked reduction in pDC release of IFN-α/λ to influenza, but it also stimulates enhanced release of IL-10 with the potential to further impair adaptive responses as well as enhanced release of IL-6 and IL-1β both of which potentially will worsen systemic inflammation." (PMID 25831059, 2015). "To assess whether IL-17A was indeed a mediator of IL-1β driven neutrophilia we neutralized IL-17A during influenza infection of LPS/elastase treated mice." (PMID 24918427, 2014). "Interestingly, a similar analysis on patient group infected with H1N1pdm09indicated that, while majority of cytokines clustered similar to the seasonal flu patients, a distinct group of cytokines including IL-1b, IL-9, IL-17 and VEGF clustered differently." (PMID 24505273, 2014). "As we observed an increase of IL-1β protein in the lungs of LPS/elastase treated mice upon influenza infection, we hypothesized that it also promotes innate immune responses and influences pulmonary function during exacerbations." (PMID 24918427, 2014). "Hence, IL-1β driven neutrophilia during influenza infection of LPS/elastase exposed mice was mediated by IL-17A in the early phase of infection, but became independent of IL-17A." (PMID 24918427, 2014). "As expression of IL-6 and TNFα were induced in our mouse model upon influenza infection, we hypothesized that IL-1β drove the observed inflammation by altering their production." (PMID 24918427, 2014). "A recent paper showed that DCs from elderly mice exhibited decreased expression of ASC, NLRP3, and caspase-1 compared with DCs from infected young mice and the concomitant blunted IL-1β response resulted in enhanced morbidity and mortality in influenza-infected elderly mice." (PMID 24409181, 2013). "The role of IL-1β for viral clearanceand pathology during Influenza infection is very complex." (PMID 21079759, 2010). "While the antiviral protective mechanism of IRF7 in the immune response is well defined, there is evidence suggesting that MX1 may exert its anti-influenza protective effect by downregulating factors such as IL-6, IL-1β and TNFα, among others, involved in excessive cytokine response." (PMID 38932312, 2024). "Interestingly, the magnitude of caspase-1 (p = 0.012) and IL-18 (p = 0.024) production in response to influenza + R848 was greater at Day 1 compared to baseline, while the opposite was true for IL-1β (p = 0.031) and pro-IL-1β (p = 0.024) secretion in response to influenza alone." (PMID 35822051, 2021). "Thus, the potent inflammasome‐activating compound like (‐)‐maackiain could be useful clinically as an immune‐stimulating agent and supplemental influenza vaccine adjuvant to further increase caspase‐1‐augmented IL‐1β production." (PMID 32428336, 2020). "Furthermore, in RAW264.7 cells, SAHA significantly reduced the expression of TNF‐α and IL‐6 in macrophages after LPS stimulation;34 TSA also reduced the IL‐1β level in the serum of a mice model of post‐influenza pneumonia but, interestingly, the acetylation level of histone H3 was not affected." (PMID 32061096, 2020). "The requirement for B cell derived NLRP3, post influenza infection, further supports NLRP3 activity as a mechanism of IL-1β production in B cells." (PMID 40825032, 2025). "Mice vaccinated with BPZE1 as infants showed reduced production of the four pro-inflammatory cytokines TNF, IL-6, IL-1β, and IFN-γ in response to influenza infection compared to unvaccinated animals." (PMID 40612502, 2025). "In comparison to influenza and bacterial CAP, patients with AdV had higher serum IL-2, IL-1β, IL-8, IL-10, CXCL10 and MCP-1, and lower TGF-β1 concentration." (PMID 39858309, 2025).
influenza (continued). "Our observation of IL-1β production by B cells lead us to investigate if B cell intrinsic IL-1β and NLRP3 significantly impacted GCs post influenza infection." (PMID 40825032, 2025). "In the Influenza infection group, the Spring PM exposure induced elevated expression of IFN-γ, IL-1β, IL-6, IL-8, TNF-α, IL-10, MCP-1, and GM-CSF relative to the control exposure." (PMID 40671793, 2025). "For instance, during early influenza infection, TLR7/RIG-I signaling and M2 ion channel activity cooperatively promote potassium ion efflux and mtROS generation, activating NLRP3 to enhance IL-1β/IL-18 release." (PMID 40860873, 2025). "We therefore measured the levels of several cytokines, including the pro-inflammatory TNF, IL-1β, IL-6, and IFN-γ, as well as IL-4, IL-10, IL-17A, and IL-22, in BAL samples from mice 5 days after influenza challenge." (PMID 40612502, 2025). "As expected, CXCL10 and IFNα levels were highest in influenza infection, whereas IL6, IL10, IL1β, and PROK2 (which is highly inducible in macrophages by LPS and other TLR2/4 agonists) reached higher levels in the bacterial infections." (PMID 39395995, 2024). "Role of Hypercytokinemia/hyperchemokinemia in the Pathogenesis of Influenza pathway was found to be significantly upregulated in the severe group’s monocytes with DEGs of AREG, CCL3, CCL4, CXCL8, IL1B, and ISG15 (coverage = 7% and p < 0.001)." (PMID 37495649, 2023). "In addition, tissue barrier maintenance and repair by unconventional T cells may be important in protection against influenza; for example, iNKT cells stimulated by IL-1β and IL-23 produced IL-22, which protected the lung epithelium from influenza-mediated damage." (PMID 37536148, 2023). "At 7 dpi with influenza, BAL from mice exposed to e-cigarette aerosol generated from the carrier VG/PG or from VG/PG/Nic had significantly higher levels of IFN-γ, TNFα, IL-1β, IL-6, IL-17A, and MCP-1 compared to mice exposed to air." (PMID 36999019, 2023). "The analysis using CytoHubba, TNF, IL10, IL-6, IL-1B, JUN, and MAPK1 was found to have the highest average scores and identified as crucial targets for the anti-influenza efficacy of TFA." (PMID 35123452, 2022). "The core network, including the pro-inflammatory TNFα, IL-6, IL-1β, MAPK, and RIG-I receptor signaling pathways, is further confirmed as the critical target of TFA anti-influenza efficacy." (PMID 35123452, 2022). "A core network containing the pro-inflammatory TNFα, IL-6, IL-1β, MAPKs, and RIG-I receptor signaling pathway was further confirmed as the crucial targets for anti-influenza efficacy of TFA." (PMID 35123452, 2022). "With the merger of PPI network, we have identified a core network, including TNF, IL-6, IL-1B, JUN, and MAPK1, as crucial targets of the anti-influenza efficacy of TFA." (PMID 35123452, 2022). "Azithromycin and other macrolides, like bafilomycin A1, erythromycin, and clarithromycin were found to impede the making of IL-1β, IL-6, IL-8, TNF-α, and ICAM-1 in influenza- and RV-modeled infections." (PMID 33937285, 2021). "For instance, Th17 cell effector cytokines (IL-1β, IL-17A, and IL-22) are upregulated in the plasma of patients with laboratory-confirmed A (H3N2) influenza and/or HPIV infections." (PMID 34602860, 2021). "IL-1β production following SARS-CoV-2 stimulation was below detection limit in 10 individuals before vaccination, and in 15 individuals after influenza vaccination." (PMID 34695164, 2021). "It has been shown that influenza upregulates TNF-α, interleukin (IL)-1β, and IL-6 and that these cytokines increase trypsin expression in endothelial cells." (PMID 33562193, 2021). "RANTES, IL-1β, IL-6, and TNF-α induced by influenza result in pro-inflammatory Th1-type immune responses in the infected host." (PMID 32269562, 2020).